LDHB (lactate dehydrogenase B)
Diseases named in the same sentence as LDHB in open-access papers (continued):
Sharing a sentence is not in itself a finding about the gene and the disease.
cancer (continued). "Suppressed expression of LDHB led to a glycolytic transition and revealed the role of suppressed LDHB in promoting proliferation, invasion, and migration of cancer cells under hypoxic condition." (PMID 31146503, 2019). "Patients with basal-like cancers expressed high LDHB and presented pathological complete response (pCR) to neoadjuvant chemotherapy." (PMID 31146503, 2019). "Our in vivo and in vitro data indicate that the specific deacetylation of LDHB by SIRT5 is essential for cancer development." (PMID 30443978, 2019). "LDHB plays a major role in metabolic adaptability of cancer cells by controlling lysosomal activity and autophagy enabling oxidative phenotype cancer cells to use lactate preferentially over glucose, leading to cell proliferation in both types of cells." (PMID 31146503, 2019). "After the cell proliferation advantage afforded by SIRT5‐mediated LDHB deacetylation to cancer cells in vitro was verified, we performed xenograft studies in vivo." (PMID 30443978, 2019). "The post-translational mechanism, by which LDHB is regulated during autophagy in cancer cells, implicates sirtuin 5 (SIRT5)." (PMID 31035592, 2019). "LDHB is upregulated as well as required only in certain cancer genotypes, dependent on aerobic glycolysis." (PMID 31035592, 2019). "Cancer cells demonstrate metabolic adaptability and in a scenario of glucose deprivation, LDHB helps in sustaining autophagy via lactate." (PMID 31146503, 2019). "In this study, we identified an important post‐translational mechanism by which LDHB is regulated during autophagy in cancer cells." (PMID 30443978, 2019). "LDHB‐mediated autophagy transfers protons to lysosomes and thus contributes to pH homoeostasis in glycolytic cancer cell." (PMID 30443978, 2019). "SIRT5 a binding partner of LDHB, promotes LDHB enzymatic activity by deacetylating LDHB at lysine-329 position leading to increased autophagy and accelerated growth of cancer cells." (PMID 31146503, 2019). "Analysis of the gene and protein expression of LDHB have shown its specific upregulation in basal-like/triple-negative breast cancer cell lines and tumors, as compared with luminal cancers." (PMID 31035592, 2019). "As molecular regulation of LDHA and LDHB in different cancer remains obscure, we also review signaling pathways regulating LDHA and LDHB expression." (PMID 31146503, 2019). "Together, these results revealed that LDHB S162 phosphorylation releases the substrate-inhibition by pyruvate, therefore boosting the catalytic efficiency of lactate generation in cancer cells." (PMID 31804482, 2019). "One of the post-translational mechanisms of LDHB regulation in cancer cell autophagy is via binding with protein Sirtuin 5 (SIRT5)." (PMID 31146503, 2019). "The results indicated that the expression level of LDHB in the cancer tissues was higher than that in the paracancerous tissues." (PMID 30419950, 2018). "(A) The Wilcoxon signed rank test was applied to compare the difference in LDHB expression between cancer and paracancerous tissues." (PMID 30419950, 2018). "An increasing number of studies investigated the role of LDHB in several subtypes of cancer, but its role remains elusive and poorly characterized." (PMID 29326883, 2017). "Lactate is taken up by oxidative cancer cells, converted in pyruvate by the isoform B of lactate dehydrogenase (LDHB), and used for mitochondrial ATP production." (PMID 29234677, 2017). "The targeting LDHB activity inhibits the proliferation of cancer cells preferentially to normal differentiated cells." (PMID 28937628, 2017). "LDHA has been implicated in the pathogenesis and progression of many cancer types and recent proteomic studies have also shown LDHB to be strikingly increased in cancer cells." (PMID 28086232, 2017). "These genes included ANKLD1, AXL, CAV1/2, LDHB, ETS1, IFI16, PTRF (cavin), KIAA1199 and VIM, which have previously been linked to drug resistance in breast and other cancers." (PMID 26646320, 2016).
cancer (continued). "We compared the expression of LDHB protein between 75 matched normal/cancer specimens from the same patients." (PMID 26426634, 2015). "Lactate dehydrogenase B (LDHB) is widely expressed in adult somatic tissue and plays important roles in the development of human cancers." (PMID 26426634, 2015). "Overexpression of LDHB according to cancer EST analysis is also pointing to a possible utilization of lactate for the oxidative metabolism." (PMID 25243088, 2014). "One contributing factor leading to decreased ECAR in the aggressive cancer cells relative to the preneoplastic T1K cells is the increase in LDHB." (PMID 24086712, 2013). "Cellular metabolism and transportation related genes (ALDOA, SLC16A3, TPI1, LDHB, KCNQ5, and PGM1), which are implicated in human cancer, also remained upregulated even 2-month after radiation exposure." (PMID 23216862, 2012). "This underscores the therapeutic necessity of targeting both LDHA and LDHB in cancer." (PMID 40940446, 2025). "Collectively, this work not only highlights the potential of repurposing natural compounds for LDHB inhibition but also provides a foundation for the rational design of isoform-selective therapeutics targeting metabolic dysregulation in cancer and other diseases." (PMID 40733189, 2025). "To further characterize the function of LDHB in suppressing lipid peroxidation-associated cell death, we combined LDHB silencing with RSL3 treatment, which irreversibly blocks GPX4, an essential regulator of ferroptotic cancer cell death." (PMID 40090955, 2025). "However, to the best of our knowledge, there is only one report in the literature describing how targeting LDHB affects cancer therapy response." (PMID 40158058, 2025). "LDHB favors the oxidation of lactate to pyruvate and has been reported to play an essential role in the progression of tumors from different entities, but its control during cancer progression remains poorly understood." (PMID 40790017, 2025). "Thus, the aim of this study is to elucidate how LDHB silencing affects DNA damage levels in cancer cells, either by itself or when combined with radiotherapy." (PMID 40158058, 2025). "Indeed, LDHB gene expression negatively correlated with the expression of AIFM2, which encodes FSP1, in the Cancer Cell Line Encyclopedia and also in the 10967 samples included in the TCGA PanCancer Atlas." (PMID 40090955, 2025). "Also, silencing LDHB did not decrease SLC7A11 expression in KRAS wild-type cancer cells; in fact, an increase in SLC7A11 was observed in HT1080 cells after LDHB silencing, but LDHB silencing still sensitized KRAS wild-type cancer cells to GPX4 inhibition." (PMID 40090955, 2025). "Lactate dehydrogenase B (LDHB) could be dysregulated in specific cancer types depending on the glycolytic requirements, while most of the time, LDHB is silenced by promoter methylation." (PMID 41154605, 2025). "However, we previously demonstrated that LDHB silencing dramatically reduces GSH levels in cancer cells." (PMID 40790017, 2025). "Subsequently, we aimed to test our hypothesis that the nucleotide depletion induced by LDHB silencing sensitizes cancer cells to cisplatin treatment." (PMID 40790017, 2025). "All 16 cancer cell lines tested in this study were sensitive to LDHB silencing." (PMID 40090955, 2025). "It was shown before that LDHB controls lysosome activity and autophagy in cancer cells." (PMID 40090955, 2025). "Indeed, in all four cancer cell lines tested, RT resulted in extensive mitochondrial lipid peroxidation, which was further enhanced when combined with LDHB silencing." (PMID 40090955, 2025). "Lactate dehydrogenase B (LDHB) is known to fuel cancer cells by converting lactate to pyruvate." (PMID 40090955, 2025).
cancer (continued). "As lactate in the TME may promote glutamine uptake of cancer cells, and LDHB is a key rate‐limiting enzyme in lactate biosynthesis, it was speculated whether the enhanced LDHB in GPER‐activated CAFs promoted glutamine uptake in TNBC cells." (PMID 39690134, 2024). "Knocking down LDHB can inhibit cancer progression in these malignancies." (PMID 39213172, 2024). "When LDHB is silenced, selective inhibitory effects on cancer proliferation have been confirmed." (PMID 39678492, 2024). "Additionally, an enhanced glutamine content in the medium and a decreased glutamine content in cancer cells co‐cultured with LDHB knockdown CAFs indicated that downregulating LDHB partially inhibited glutamine uptake by TNBC cells." (PMID 39690134, 2024). "In the current study, we found there was a close correlation between LDHA and LDHB expression levels and multiple TIIC subsets, i.e., B cells, cancer-associated fibroblast, CD4+ T cells, CD8+ T cells, endothelial cells, and neutrophils, and massive immunoinhibitors such as VTCN1." (PMID 37547725, 2023). "In addition, some cancer cells take up lactate and use it as fuel for mitochondrial oxidative metabolism, converting it back into pyruvate with lactate dehydrogenase B (LDHB)." (PMID 37568758, 2023). "Lactate dehydrogenase, LDHA, and LDHB are important targets for cancer therapy." (PMID 37762231, 2023). "In summary, the downregulation of LDHB in cancer might be due to epigenetic modifications such as DNA methylation and histone deacetylation, as well as dysregulated microRNA expression." (PMID 37547725, 2023). "As a marker of prominent cancer-specificity, LDHB has a median abundance of 97%." (PMID 36900348, 2023). "Understanding the mechanisms behind LDHB downregulation may help to identify potential therapeutic targets for cancer." (PMID 37547725, 2023). "Many studies have found that LDHB could promote the proliferation, migration, and invasion of cancer cells by regulating apoptosis and autophagy." (PMID 35978348, 2022). "Therefore, LDHB can be regarded as a prognostic marker of cancer recurrence and poor overall survival of OS." (PMID 36059961, 2022). "An essential role of LDHB in the progression of various cancers has been increasingly reported." (PMID 35669414, 2022). "For instance, the promoter of LDHB is hypermethylation in cancer cells, which could upregulate the LDHA/LDHB ratio and further promote the production of lactate." (PMID 36319992, 2022). "Whether the different contributions of LDHA and LDHB to histone lactylation is a general feature in cancers requires further efforts." (PMID 35637958, 2022). "Therefore, combined targeting of LDHA and LDHB will be more effective anti-glycolytic-based therapeutic strategies for cancer treatment." (PMID 36612084, 2022). "We could create synthetic lethality by adding hemin with a lower dosage of MCT1 and LDHB inhibitors, although MCT1 and LDHB inhibitors at higher concentrations are reported to suppress cancer growth." (PMID 35406740, 2022). "Application of this pharmacology antagonist and/or the genetic engineering technology may facilitate our knowledge of the LDHB function in cancer." (PMID 36612084, 2022). "Additionally, long-term knockdown of LDHB inhibited cancer cell growth and induced cell senescence in vitro and in vivo." (PMID 35669414, 2022). "Interestingly, LDHB also plays a crucial role in lysosomal activity and autophagy, while silencing of LDHB leads to selective inhibition of cancer cell proliferation." (PMID 36551514, 2022). "Additionally, miR-375 and miR-335-5p can also directly suppress the LDHB expression to inhibit the growth, proliferation, and migration in the carcinoma cells." (PMID 36612084, 2022). "Furthermore, in liver cancer, decreased expression of LDHB is reported to induce mitochondrial defects and thereby, carcinoma cell invasiveness." (PMID 36612084, 2022).
cancer (continued). "Indeed, the LDHA isoform preferentially converts pyruvate to lactate, which is typical of cancer cells, while the LDHB isoform preferentially converts lactate to pyruvate." (PMID 34205977, 2021). "LDHB, induced by androgen-specific signaling, is a well-known metabolic enzyme involved in lactate production, which leads to bypassing of oxidative phosphorylation, especially in glycolic cancer cells." (PMID 34680521, 2021). "In particular, LDHB expression may serve as a predictive metabolic marker for therapeutic response in various cancers." (PMID 34822416, 2021). "Considering pyruvate could also be increased following a large influx of glucose into cancer cells under hypoxia, the pyruvate level was also compared following the knockdown of LDHB." (PMID 33806179, 2021). "However, the phenomenon of reversal of cancer-specific metabolism through LDHB activation is a unique method." (PMID 33806179, 2021). "Interestingly, this LDHB-dependent metabolism increases the autophagy flux along with increased acidification of the lysosomes in cancer cells." (PMID 33364196, 2020). "Namely, the results show significantly higher total LDH activity and provide evidence for the “harlequin phenomenon” in terms of non-homogenous protein localization of LDHB in cancer-associated adipose tissue." (PMID 33353120, 2020). "LDHB is largely used by cancer cells to bypass oxidative phosphorylation process to produce lactate directly from pyruvate to promote the cell proliferation, while transactivated by the key tumorigenic driver, signal transducer and activator of transcription 3 (STAT3)." (PMID 32850805, 2020). "Thus, switching the catalytic direction of LDHB would be an efficient strategy for cancer cells to fit fluctuating metabolic demands." (PMID 31804482, 2019). "LDHB expression in different cancers may also serve as a predictive metabolic marker for therapy response." (PMID 31146503, 2019). "Additionally, it has been established that upregulation of LDHA significantly contributes to increased glycolysis in various cancers, however, how LDHB is regulated is poorly understood." (PMID 31804482, 2019). "A recent study has shown that LDHB plays an important role in autophagy in cancer cells." (PMID 30443978, 2019). "LDHB‐mediated autophagy benefits both oxidative and glycolytic cancer cells." (PMID 30443978, 2019). "Furthermore, elevated LDHB expression had a significant impact on cancer progression and metastasis." (PMID 30443978, 2019). "However, despite contradictory results, LDHB is an important participant in carcinogenesis and is considered as a potential target for anti-cancer therapy." (PMID 30967137, 2019). "LDHB may control lysosomal acidification, vesicle maturation, and intracellular proteolysis in both oxidative and glycolytic type cancer cells." (PMID 31146503, 2019). "These included Eno1, LDHB, NPM1, PKM2 and KPNA2, which are commonly overexpressed in NSCLC, are associated with poor prognosis, and are therefore potentially relevant targets for cancer immunotherapy." (PMID 29258618, 2017). "Expression of LDHB is suppressed in many kinds of cancer due to promoter hypermethylation." (PMID 26918353, 2016). "An increasing number of studies have shown that LDHB might play a critical role in some subtypes of cancers." (PMID 25973606, 2015). "LDHB is another enzyme in the pathway that is overexpressed in cancer." (PMID 25243088, 2014). "LDHA and LDHB proteins are differentially regulated in cancer cells." (PMID 24280423, 2013). "Importantly, the observation of significant decrease of LDHB after treatment of anthracyclines DNR and DOXO as well as anthracenedione MTX thus underlies common anti-cancer effect of this group of drugs directed to the energy metabolism of cancer cell." (PMID 23443080, 2012).
cancer (continued). "Thus, identifying phytochemicals with inhibitory activity against LDHB may yield innovative strategies for cancer therapy and other LDHB-related pathologies, such as cardiovascular, neurodegenerative, and chronic liver or kidney diseases." (PMID 40733189, 2025). "Thus, we hypothesized that the nucleotide depletion induced by LDHB silencing sensitizes cancer cells to cisplatin treatment." (PMID 40790017, 2025). "Thus, we speculate that cancer cells require higher LDHB activity than normal cells to handle their increased nucleotide-related metabolic demands." (PMID 40158058, 2025). "Targeting LDHB could also offer a potential approach for cancer therapy." (PMID 39678492, 2024). "In addition, inhibiting LDHB increases apoptosis in cancer cells, in combination with chemotherapy." (PMID 36829149, 2023). "LDHB-mediated LA use supports autophagy to maintain metabolic health and cancer cells growth, indicating that the production and use of LA may be involved in the metabolic adaptation of cancer cells to support the development of metastasis." (PMID 37853445, 2023). "Under normal conditions, MP31 binds to lactate dehydrogenase B (LDHB) to suppress lactate-pyruvate conversion, and downregulation of MP31 in GBM cells was associated with increased lactate utilization, a characteristic metabolic finding of cancer cells with high tumorigenicity." (PMID 37213226, 2023). "LDHB plays an important role in the reciprocal transformation of pyruvate and lactic acid, so it is crucial to the cancer-specific Warburg effect, and thus, it may be an important cancer-related target." (PMID 35978348, 2022). "Therefore, we hypothesised that the inhibition of LDHB may be a promising therapeutic approach for targeting cancer metabolism." (PMID 34725423, 2021). "Thus, finding novel strategies aimed at LDHB in hypoxic cancer cells is warranted." (PMID 33806179, 2021). "However, how LDHB functions in these cancers is poorly understood." (PMID 31804482, 2019). "Therefore, LDHB has an important role in cancer progression." (PMID 30443978, 2019). "Thus, it was reasonable to believe that SIRT5‐deacetylated LDHB could promote the lysosomal acidification and, subsequently, autophagy, which are essential for cancer development." (PMID 30443978, 2019). "Moreover, silencing LDHB had an antiproliferative effect on cancer cells." (PMID 31035592, 2019). "Thus, targeting LDHA or/and LDHB can create the new opportunity to combat cancer cells." (PMID 31035592, 2019). "Thus, LDHB may be a promising target for cancer prevention and treatment." (PMID 40565047, 2025). "Together, our in vitro, in silico, and in vivo data indicate that LDHB and GPX4 work in parallel to suppress lipid peroxidation, particularly in mitochondria, thereby corroborating our hypothesis that LDHB is an important contributor to suppress mitochondria-associated ferroptosis in cancer cells." (PMID 40090955, 2025). "LDHB, a subunit of LDH, is upregulated in various malignant tumors and is correlated with aerobic glycolysis (Urbańska & Orzechowski, 2019)." (PMID 38952967, 2024). "Analyzing the expression of LDHs genes including LDHA, LDHB, LDHC and LDHD in all cancer types, we found that the expression of LDHA, LDHB and LDHD was higher than that of LDHC in pan-cancer." (PMID 38291366, 2024). "For example, hypermethylation of the LDHB promoter increases the LDHA/LDHB ratio, enhancing lactate formation in cancer cells." (PMID 39119332, 2024). "The increased production of lactate from pyruvate, which is typical for cancer cells, is gathered by the elevated LDH enzymes (LDHA, LDHB)." (PMID 37175655, 2023). "NNMT, LDHB, and PTBP1 have been studied for promoting cancer development, but their synergistic effects with vemurafenib are not clear." (PMID 36829149, 2023). "In HCT116 cells, LDHB K329 deacetylation performed by SIRT5 supported cell respiration and ATP synthesis, thereby promoting the growth of cancer cells also through this pathway." (PMID 36980194, 2023).